CD47 (CD47 molecule)
Diseases named in the same sentence as CD47 in open-access papers (continued):
Sharing a sentence is not in itself a finding about the gene and the disease.
tumor (continued). "Tumor cell surface molecule CD47 binds to its ligand, the signal regulatory protein α (SIRPα) on the macrophage cell surface, and provides a safety signal, blocking phagocytosis." (PMID 39660126, 2024). "The positive expression rate of CD47 in tumor tissues was significantly higher than that in adjacent tissues, with the difference being statistically significant (P< 0.05)." (PMID 39652550, 2024). "CD47, a small molecule expressed on the surface of tumor cells, functions as a “don’t eat me” mark by binding to signal-regulatory protein alpha (SIRPα), an inhibitory receptor, on tumor-associated macrophages (TAMs) and dendritic cells (DCs)." (PMID 38560565, 2024). "This system was initially used to design a strategy with CD47 antagonistic nanobodies, enhancing anti-tumor T cell priming by promoting phagocytosis of cancer cells and cross-presentation of tumor antigens." (PMID 39233526, 2024). "While dual blockade negates anti‐CD47‐mediated toxicity, the effect of combined innate and adaptive immune activation on protective tumor‐resident CD8+ T cells has yet to be fully elucidated." (PMID 39584189, 2024). "In these xenograft experiments, anti-CD47 treatment prevented both primary tumor growth and the development of metastatic disease." (PMID 38473300, 2024). "We thank Dominique Vanhecke for the design and conception of the strategy to modify T cells to express CD47 decoys in the tumor microenvironment, as well as for the initial training and supervision of the research work conducted by ES and AS." (PMID 38828721, 2024). "The NCI-H929 tumor xenograft model was used to evaluate the efficacy of the CD38/CD47 BsAbs, including IMM5605-ISA, IMM5605-DARA, IMM5605–4A8, 12C10, 26B4, 35G5, and 65A7." (PMID 38983860, 2024). "Together, these data suggest a direct role of CD8+ T cells in breast cancer tumor regression and that the mechanisms of CD47 × PD‐L1 BisAb‐mediated tumor control are regulated by CD8+ T cells." (PMID 39584189, 2024). "It was reported that tumor mtDNA inside the cytosol of DCs is increased in response to CD47 blockade, which is essential for the induction of IFN-Is and antitumor immunity." (PMID 38982116, 2024). "CD47 can interact with its receptor signal regulatory protein α (SIRPα) to inhibit the phagocytic activity of DCs and promote tumor immune escape." (PMID 39334927, 2024). "To further confirm the phenotype of ATP release in tumor tissues in vivo upon CD47-SIRPα blockade, we measured tumor tissue extracellular ATP using an ATP probe and the IVIS system." (PMID 38982116, 2024). "The high expression of CD47 can bind to SIRPα, which is on the surface of macrophages, inhibiting their antigen presentation and disrupting anti‐tumour immune responses." (PMID 38652105, 2024). "In the tumor microenvironment, cancer cells can inhibit macrophage phagocytic activity through the expression of “don’t-eat-me” checkpoint proteins (i.e., CD47 and CD24)." (PMID 38690738, 2024). "In most tumors, signal regulatory protein α (SIRPα) on the surface of macrophages often interacts with CD47 (a "don't eat me" signal) on the surface of tumor cells, limiting the ability of macrophages to phagocytose tumor cells." (PMID 38281957, 2024). "Blocking the CD47/SIRPα signaling pathway can effectively promote phagocytosis of tumor cells by macrophages in vitro and in vivo." (PMID 39513610, 2024). "The mouse anti-SIRPα antibody clone P84 has been reported to have little effect on the CD47/SIRPα interaction, and its ability to decrease tumor growth seems dependent on tumor type and treatment schedule." (PMID 38414061, 2024). "The interaction between CD47 and signal regulatory protein alpha (SIRPα) directly hinders the phagocytosis of tumor cells by macrophages, leading to a subsequent impairment in the presentation of tumor antigens to T lymphocytes." (PMID 38532108, 2024).
tumor (continued). "Here, we utilised CD47 × PD‐L1 BisAb that has been engineered with reduced affinity towards CD47 to negate erythrocyte binding, while retaining engagement with PD‐L1‐expressing cells in the tumor." (PMID 39584189, 2024). "CD47 binds to SIRPα, a receptor in various bone marrow-derived cells, and functions as an innate inhibitory checkpoint that inhibits phagocytosis against tumor cells and the activation of downstream responses." (PMID 38612630, 2024). "Based on tumor immune evasion, a series of immunotherapy approaches such as blocking CD47/SIRPα has been developed and clinically applied to tumor therapy." (PMID 38383737, 2024). "The use of the BsAbs were found to significantly improve outcomes, reducing tumor volumes when compared to either anti-CD47 or anti-PD-1/PD-L1 alone." (PMID 38261139, 2024). "The immunoglobulin protein CD47 is overexpressed in malignant tumor cells, allowing them to evade host immunity by inhibiting macrophage-mediated phagocytosis." (PMID 38474640, 2024). "Macrophage antitumor activity can be restored by simultaneously blocking the CD47-SIRPα signaling axis and inducing a prophagocytic signal via tumor-opsonizing antibodies." (PMID 38319147, 2024). "CD47-targeted drugs are in development and demonstrate certain anti-tumor activities and can improve prognosis in clinical trials." (PMID 38317230, 2024). "Tumor cells evade phagocytosis by overexpressing “don’t eat me signals”, such as CD47 and CD24, which interact with their binding partners SIRPα and SIGLEC10, respectively, that are abundantly expressed on innate immune cells." (PMID 38459166, 2024). "CD47 inhibits phagocytosis by macrophages, thereby enabling tumour cells to evade immune surveillance." (PMID 39390760, 2024). "Intriguingly, normal astrocytes are unaffected by the presence of 4N1K, suggesting that CD47 selectively enhances the proliferation of tumor cells." (PMID 39039207, 2024). "Current studies indicate that tumor cells can evade macrophage phagocytosis by binding to the SIRPα receptor on macrophages through the overexpression of CD47." (PMID 39735532, 2024). "Reports have shown that CD47 blockade mediates tumor resolution primarily through increased macrophage clearance and via enhanced antigen cross-presentation by DCs which leads to improved T cell priming." (PMID 38577107, 2024). "A significantly increased level of extracellular ATP concentration was observed in tumor tissues upon CD47-SIRPα blockade." (PMID 38982116, 2024). "Tumor cells, which often overexpress CD47, can use this signaling axis to escape the immune recognition and inhibitors of this axis are tested in clinical trials already." (PMID 38357194, 2024). "This aligns with reports that the anti-tumor activity of Siglecs depends on an active Fc-FcR interaction, similar to what is required for CD47 blockade." (PMID 39659795, 2024). "TCR or CAR T cells expressing 47E are resistant to clearance by macrophages after treatment with anti-CD47 antibodies, and mediate substantial, sustained macrophage recruitment to the tumour microenvironment." (PMID 38750365, 2024). "Various tumor cells suppress TAMs’ phagocytosis by elevating the expression of CD47 protein, ultimately enabling immune escape." (PMID 38273373, 2024). "CD47 is a cell-surface ligand that is overexpressed in various malignancies and that binds to SIRPα on macrophages to promote tumor cell evasion of phagocytosis." (PMID 38464520, 2024). "GenSci059 selectively binds to CD47, effectively blocks the CD47/SIRPα axis signaling pathway and enhances the phagocytosis effects of macrophages toward tumor cells." (PMID 38429732, 2024). "In NSCLC-bearing mouse models, a significant delay in tumor growth was observed with anti-CD47 Ab and anti-CTLA4 therapy alone compared to the control group." (PMID 38398223, 2024).
tumor (continued). "Genetically modified SIRPa-Fc can block CD47, and these can therefore be delivered by OVs to hone an immune response toward tumor cells by macrophages exerting a therapeutic benefit." (PMID 38533720, 2024). "Tumor cells typically overexpress CD47, triggering the inhibitory receptor SIRPα expressed on macrophages to evade phagocytosis and antitumor immunity." (PMID 39697556, 2024). "CD47 positivity in tumor tissues (52%) was significantly higher than in adjacent tissues (20%) (P<0.001), with expression localized to the cell membrane." (PMID 39652550, 2024). "Research has indicated that diminishing the expression of CD47 on tumor cells significantly enhances TAMs’ ability to eliminate tumor cells." (PMID 38273373, 2024). "CD47 primarily inhibits the phagocytosis of tumor cells by macrophages by binding to the surface receptor SIRPα and sending a “don’t eat me” signal." (PMID 38370407, 2024). "The indirect effects of CD47 signaling on other immune cells includes decreased tumor antigen presentation due to inhibition of phagocytosis, thus limiting T-cell activation." (PMID 38493445, 2024). "CD47 is an extracellular ligand of SIRPα, and the combination of SIRPα and CD47 reduces the phagocytic activity of macrophages by producing inhibitory signals, resulting in tumor immune escape." (PMID 38560565, 2024). "Anti-CD47 mAb delivered i.t. in combination with 2′3′-Cyclic GMP-AMP (cGAMP) seven days after tumor implantation led to a complete cure in 5/9 treated E0771 tumor-bearing mice after a single injection." (PMID 38803496, 2024). "Based on the current paradigm, the interaction between CD47 on tumor cells and SIRPA on macrophages leads to inhibition of tumor phagocytosis." (PMID 38920727, 2024). "The research utilized a subcutaneous transplantation tumor model of NSCLC in mice, observing significant anti-tumor effects with the combination therapy targeting CD47 and CTLA4." (PMID 38398223, 2024). "CD47 is the most studied "don't eat me" signal that is overexpressed on tumor cells and inhibits macrophage activity through interaction with its receptor SIRPα." (PMID 38773982, 2024). "As CD47 is expressed on all human cells, the immune response needs to be limited to tumor cells as intended target." (PMID 38720892, 2024). "We then incorporated cells found within a tumor which either express high (CAFs) or low (B16.F10 tumor cells) levels of CD47 as determined by flow cytometry." (PMID 38577107, 2024). "The interaction between CD47 and SIRPα triggers “don’t eat me” signals from macrophages, inhibiting phagocytosis and enabling tumor cells to evade immune surveillance." (PMID 38398223, 2024). "A series of preclinical studies have demonstrated that the gene expression of CD24 and CD47 is beneficial to increase the anti-tumor phagocytosis of macrophages." (PMID 38787372, 2024). "By combining anti-CD47 mAb with ani-PD-L1 mAb, the promotion of tumor cell phagocytosis in vitro was obtained as well as suppression of growth of the tumor observed in vivo, which showed the synergy between innate and adaptive ICIs." (PMID 38892394, 2024). "Both GD2 and CD47 have been highly expressed in glioblastomas and, when combined, inhibit tumor progression." (PMID 38892305, 2024). "Numerous studies of CD47/SIRPα blockades by targeting either CD47 or SIRPα have demonstrated potent anti-tumor action in preclinical models and clinical studies." (PMID 39040441, 2024). "While the immune-suppressive role of CD47 on the cell surface of tumor cells has been characterized to a great extent, mechanisms underlying its regulation during human cancer progression are only beginning to emerge." (PMID 39742254, 2024). "Critically, CD47 × PD‐L1 BisAb treatment resulted in significantly greater IFNγ‐producing CD8+ T cells in the tumor and spleen than anti‐PD‐L1 alone." (PMID 39584189, 2024).
tumor (continued). "Our in vitro studies demonstrate that GenSci059 effectively blocks the interaction between CD47 and its inhibitory receptor SIRPα, leading to a dose-dependent promotion of tumor cell phagocytosis by both mouse and human macrophages." (PMID 38429732, 2024). "A panel of BsAbs targeting CD38 and CD47 developed based on the “mAb-tarp” platform showed potent tumor-killing ability in vitro and in vivo." (PMID 38983860, 2024). "CD47 is a surface protein that has been shown to be upregulated in tumor cells and subsequently binds the receptor SIRPα on phagocytic cells to block the otherwise ensuing phagocytic response." (PMID 38893093, 2024). "In this study, it was observed that targeting CD47 led to an upregulation of CTLA4 levels in tumor cells, as evidenced by the IHC and IF assays." (PMID 38398223, 2024). "Further, tumor cells can express CD47, which, as a “don’t eat me” signal to the host innate immune system, plays a role in tumor immune evasion." (PMID 38504984, 2024). "CD47 gene expression was found to be consistently high across all tumor indications profiled in TCGA, with a narrow range of variability." (PMID 38319147, 2024). "CD47 is a surface receptor expressed by tumor cells that engages SIRPα on phagocytes such as macrophages and dendritic cells, inhibiting macrophage phagocytosis." (PMID 38473300, 2024). "The proportion of tumor-infiltrating CD45+ immune cells was elevated in response to the combination group compared to the single-agent treatment groups (anti-CD47 Ab and anti-CTLA4 Ab alone)." (PMID 38398223, 2024). "Monoclonal antibodies or fusion proteins targeting CD47 have the potential to disrupt this “don’t eat me” signal, facilitating the macrophages mediated phagocytosis of tumor cells and promoting an immune response against the tumor." (PMID 38429732, 2024). "BsAbs had higher affinity and binding activity to the CD38 target than those to the CD47 target, decreasing the potential on-target potential and off-tumor effects." (PMID 38983860, 2024). "SIRPα-CD47 interaction is exploited by cancer cells to suppress anti-tumor activity of myeloid cells, therefore emerging as a novel immune checkpoint for cancer immunotherapy." (PMID 38843278, 2024). "Sotorasib was able to inhibit tumor growth as a single agent, yet the greatest inhibition of tumor growth occurred upon sotorasib treatment of a CD47-KO cell line." (PMID 38483480, 2024). "Another IC is the cluster of differentiation 47 (CD47), which binds to signal regulatory protein alpha (SIRPα) of membrane macrophages to inhibit tumor cell phagocytosis." (PMID 38339019, 2024). "In preclinical tumor-bearing mouse models, simultaneous blockade of CD47/SIRPα and PD-1/PD-L1 further inhibits tumor growth." (PMID 38462636, 2024). "The higher binding affinity to CEACAM5 as compared to CD47 enables the selective blockade of CEACAM5-expressing tumor cells." (PMID 38720892, 2024). "Prior to tumor inoculation, CD47 knockout (KO) B16F10 cells were treated with 2.5 μM MPS1i (reversine) or the equivalent volume of DMSO vehicle control." (PMID 38805560, 2024). "Subsequently, it was discovered that CD47 is commonly over expressed on most tumor cells like AML, MDS, NHL as a macrophage checkpoint." (PMID 38322418, 2024). "Strategies that allow for the controlled release of CD47 antibodies responsive to the tumor microenvironment have reduced this systemic toxicity." (PMID 39713206, 2024). "Two possible mechanisms include the UCAR-T cells directly killed tumor cells and enhanced the phagocytosis of macrophages by secreting anti-CD47 nanobody hu404-hfc fusion." (PMID 39040441, 2024). "CD47 is not only present on tumor cells but also expressed on the surface of erythrocytes, platelets, and hematopoietic stem cells." (PMID 38429732, 2024). "TSP-1 reprograms the TME via binding to CD36 and CD47 to induce tumor and endothelial cell apoptosis as well as immune modulation in the TME." (PMID 38218979, 2024).
tumor (continued). "Our results indicate that NextA and anti-CD47 moderately decrease tumor growth as stand-alone therapies compared to vehicle control and that combining these agents further reduces tumor growth in SM1-bearing mice." (PMID 38414061, 2024). "To determine if this represents an adaptive response suggesting vulnerability to phagocytosis, we examined untreated and HOSU-53–treated AML cells together with the B6H12 antibody that interferes with binding of SIRP-α on murine macrophages with tumor CD47." (PMID 38646934, 2024). "Previous research has indicated that CD47 is upregulated in various tumor cells and is positively correlated with an adverse prognosis in breast, gastric, lung, and ovarian cancers." (PMID 38398223, 2024). "At the same time, macrophage-mediated tumor cell phagocytosis by using anti-CD47 antibodies to block the anti-phagocytic CD47-SIRPa interaction has shown promise in preclinical xenotransplantation of various human malignancies." (PMID 38393698, 2024). "The immune checkpoint CD47 is highly expressed in tumors, inhibiting tumor antigen presentation and mediating immune suppression." (PMID 39223632, 2024). "CD47 has also been detected in exosomes released by platelets, erythrocyte-derived microvesicles, human mesenchymal stem cells, T cells, and CD47-overexpressing normal or tumor cells (transgenic or native)." (PMID 38426113, 2024). "It was also recently found that elevated expression of the CD47 molecule on tumor cells is characterized by reduced removal by phagocytes expressing the CD47 counter-receptor SIRPα." (PMID 38473328, 2024). "The ligand of CD47, SIRPα, is mainly expressed on macrophages and when their interaction occurs, its downstream signaling within tumor cells results in the dephosphorylation of multiple substrates, keeping tumor cells from phagocytosis by macrophages." (PMID 39003350, 2024). "Lastly, the approach of tapping the anti-tumor function of TAMs, exemplified by SIRP1α–CD47 inhibitors, leverages the innate anti-tumor functionalities of certain TAM subsets to impede or halt tumor growth." (PMID 38185636, 2024). "Tumor patients having the highest CD47 expression profile at baseline showed the greatest CD4+ and CD8+ T-cell influx post NACT and displayed a better prognosis." (PMID 39138571, 2024). "Researchers are developing safer strategies to address these issues, including identifying tumor-specific CD47 epitopes and creating bispecific antibodies." (PMID 39409110, 2024). "Immunohistochemical analysis revealed that the combination of anti-angiogenic therapy and CD47 blockade resulted in a reduction of tumor angiogenic vasculature and infiltrated M2-like macrophages, in comparison to the use of anti-CD47 therapy alone." (PMID 38532108, 2024). "With continued research, CD47 overexpression has been observed in various tumor types, influencing tumor cell behavior through direct and indirect pathways." (PMID 39652550, 2024). "Thrombospondin-1, as one of the ligands of CD47, typically inhibits tumor angiogenesis by blocking endothelial cell proliferation and chemotaxis." (PMID 38398223, 2024). "This study aimed to elucidate the significance of CD47 in the context of emerging anti-tumor targeting approaches." (PMID 38493445, 2024). "Together, these data reveal an important role of type I interferons on tumor cell metabolic reprograming for tumor immunotherapy and provide rational strategies harnessing this mechanism for enhanced efficacy of CD47-SIRPα blockade." (PMID 38982116, 2024). "This suggests that the combination of tumor-specific CD47 inhibition and IL-12 production can synergistically enhance macrophage-mediated immunotherapy." (PMID 38543240, 2024). "For instance, IBI322, was designed to improve therapeutic selectivity and efficacy by preferentially binding to PD-L1+CD47+ tumor cells, inducing tumor cell phagocytosis while minimizing impact on CD47+PD-L1− cells like red blood cells." (PMID 38475778, 2024).